CREBBP (CREB binding lysine acetyltransferase )
Diseases named in the same sentence as CREBBP in open-access papers (continued):
Sharing a sentence is not in itself a finding about the gene and the disease.
tumor (continued). "Regarding HATs, a recent study has shown that CREBBP/EP300 mutations contributed to both tumor progression and an aberrant TME in DLBCL." (PMID 35326620, 2022). "In this study, we performed the genomic analysis in a large cohort of DLBCL patients and showed that CREBBP/EP300 mutations were significantly associated with tumor progression." (PMID 33431788, 2021). "Single-cell RNA sequencing further confirmed that the presence of increased macrophages in tumor microenvironment was related to CREBBP/EP300 mutations." (PMID 33431788, 2021). "CREBBP is mutated and lost in human cancers and plays a tumor suppressor role in pathophysiological processes." (PMID 34887753, 2021). "Meanwhile, underlying mechanisms of CREBBP/EP300 mutations on TAM polarization within the tumor microenvironment were studied both in vitro and in vivo." (PMID 33431788, 2021). "This analysis showed that CREBBP mutations are dominant clonal events in most cases accounting for 78.1% of tumor cells (median 95 CI 49.7–99.0%)." (PMID 32555149, 2020). "CREBBP mutations often result in loss of tumor-suppressive functions and are difficult to target therapeutically." (PMID 33381456, 2020). "Both proteins encoded by EP300 and CREBBP are suggested as tumor suppressors and indicative of poor prognosis in ESCC." (PMID 29506494, 2018). "Apart from the three genes (RB1, BCOR, CREBBP) that showed somatic mutations in at least 2 different tumors, there were 199 other genes that were mutated in a single tumor only." (PMID 27126562, 2016). "It was reported that Co-regulator expression of CREBBP/p300 had been associated with lower tumor grade." (PMID 27557076, 2016). "While all of the tumor cells at both diagnosis and relapse shared the two SNVs in CREBBP and RGS11, five additional mutations in NRF1, MARCKS, USP11, ELK1, and MYC were detected at diagnosis." (PMID 26527318, 2016). "In line with this, an earlier mouse study showed that heterozygous CREBBP loss led to increased neoplasia over wild-type mice." (PMID 24622842, 2014). "However, another study revealed that CREBBP mutations promote the proliferation of B‐lymphoma cells and the polarization of tumor‐related macrophages to the M2 phenotype by inhibiting histone acetylation." (PMID 40318003, 2025). "Huang Y.H., Cai K., Xu P.P., Wang L., Huang C.X., Fang Y., Cheng S.,Sun X.J., Liu F., Huang J.Y., Ji M.M., Zhao W.L. CREBBP/EP300mutations promoted tumor progression in diffuse large B-cell lymphomathrough altering tumor-associated macrophage polarizationvia FBXW7-NOTCH-CCL2/CSF1 axis." (PMID 41541561, 2025). "Since the missense mutation of the CREBBP gene suspected to appear in the early tumor precursors, it presents in all malignant cells and mutation analysis in this gene can be performed at any stage of disease development (initial or relapse) and in any tumor site." (PMID 40725159, 2025). "While the tumor-specific frequency of CREBBP and EP300 mutations constrains the analysis in small cohorts, these findings further support their role as biomarkers of immunotherapy response and underscore the need for expanded datasets and prospective validation." (PMID 41301688, 2025). "Tumor mutations in CREBBP/EP300 and CASP8 were significantly associated with Th2 infiltration." (PMID 38672668, 2024). "Although it is known that genome ploidy contributes to tumour malignancy and inferior survival, we found that clonal mutations of CREBBP/EP300 associated with acquired genome duplication cause relapse and thereby provide a clear genetic mechanism of drug resistance." (PMID 38480884, 2024). "Therefore, we decided to study the effects of MYCN overexpression and a simultaneous loss of CREBBP to understand tumor driving mechanisms." (PMID 37407554, 2023).
tumor (continued). "EP300/CREBBP inhibitors are being trialled in EP300-, ARID1A- and CREBBP-deficient tumours." (PMID 35267442, 2022). "We conducted genomic analysis using paired tumor tissue samples at diagnosis and relapse and observed frequent occurrence of mutations in CREBBP and EZH2, which are involved in lymphomagenesis and progression as a chromatin regulator, as well as mutations in BNFRSF14 and BCL2 as previously reported." (PMID 36199784, 2022). "A higher percentage of nuclear NICD (intracellular portions of NOTCH1)-positive cells was observed in tumor samples of CREBBPmut/EP300mut patients than those of CREBBPwt/EP300wt patients, confirming the link of CREBBP/EP300 mutations with NOTCH signaling activation." (PMID 33431788, 2021). "Furthermore, complete loss of CREBBP also accelerated tumor development in the autochthonous mouse model and significantly reduced overall animal survival." (PMID 31827074, 2019). "Finally, the CREBBP gene was altered in 1 tumor (1.1%), showing one already known frameshift mutation localized outside the main domains of the protein." (PMID 31548566, 2019). "The redundant targets of CREBBP and EP300 may be essential for tumor cell survival because DLBCL cell lines with truncating mutations of CREBBP are sensitive to knock-out or pharmacologic inhibition of EP300." (PMID 31788471, 2019). "In ESCC, CREBBP mutations and deletions of have been recurrently detected, and CREBBP acetyltransferase activities may be tumor suppressive." (PMID 27556701, 2016). "CREBBP is involved in multiple signal transduction pathways where is functions as a transcription cofactor for genes that encode many different proteins, such as oncoproteins, transforming viral proteins, and tumor-suppressor proteins." (PMID 25915404, 2015). "Interestingly, there is recent evidence from multiple tumour types that histone deacetylase inhibitors could offer exceptionally high response rates in tumours harbouring CREBBP pathogenetic or unknown variants." (PMID 36085291, 2022). "Interestingly, in FL, CREBBP mutations are correlated with reduced tumor expression of genes involved in the MHC class II antigen presentation pathway, and also with decreased B-cell receptor (BCR) and interferon signaling, accompanied by reduced proliferation of tumor-infiltrating T cells." (PMID 35022084, 2022). "Therefore, CREBBP is implicated as a novel candidate tumor suppressor gene in a subset of GBMs." (PMID 25423036, 2014). "Recurrent mutations in key epigenetic regulators such as EZH2, KMT2D, CREBBP, and TET2 lead to altered chromatin states, repression of tumor suppressor genes, and enhanced oncogenic signaling." (PMID 40943058, 2025). "Cox univariate analysis further revealed a significant prediction of clinical outcomes in patients with CREBBP‐mut scores, as well as factors, such as age, invasiveness, and tumor stage." (PMID 40693457, 2025). "In B-lymphoma cells and murine models, the muting of CREBBP/EP300 in tumor cells resulted in polarization of TAMs towards the M2 phenotype by activating the NOTCH signaling pathway and downstream CCL2/CSF1 axis." (PMID 40216772, 2025). "Co-occurring CN loss and hypomethylation events were more prevalent in LUSC, affecting TSGs including NCOR1 (29 of 59 tumor regions), CDKN2C (28 of 59 tumor regions), CREBBP (26 of 59 tumor regions) and RPL22 (9 of 59 tumor regions)." (PMID 40931149, 2025).
tumor (continued). "Among these genes, PDE4D, LRP1B, CREBBP, and NCOR1 were previously associated with deletions in BC tumor tissue, which favors tumorigenesis or progression." (PMID 40801146, 2025). "Using Tumor Immune Estimation Resource (TIMER) data, we found patients with CREBBP, EP300, CHD7 mutations and PRDM9 amplifications associated with low B‐cell infiltration, potentially aiding tumor growth." (PMID 40693457, 2025). "Taken together, our results establish coding mutations in CREBBP and EP300 as functionally and clinically relevant alterations linked to genomic instability and enhanced tumor immunogenicity." (PMID 41301688, 2025). "Histone acetylation disruption is commonly linked to CREBBP mutations in NHL, which results in aberrant gene expression and accelerates tumor growth." (PMID 40321894, 2025). "Taken together, these results demonstrate that CREBBP‐mut scores are strongly correlated with clinical factors, such as invasiveness, tumor stages, and molecular subtypes." (PMID 40693457, 2025). "In this study, we introduce a BCOR::CREBBP fusion in an adult patient with a right temporomediobasal tumor and methylation class “CNS tumor with BCOR/BCOR(L1)-fusion”." (PMID 38637838, 2024). "It is therefore of high clinical value to maximize the anti-tumor effects of HDAC3 inhibition in the broader population of DLBCL patients, in addition to the subset of cases harboring CREBBP mutations." (PMID 39117798, 2024). "Other genes that have been proven to be associated with tumor initiation or progression like PIK3CA, ATM, PTEN, and CREBBP are also present in PDTC and ATC with a mutation frequency higher than 5%." (PMID 39235852, 2024). "Instead, the tumor showed CREBBP::BCORL1 fusion and pathogenic mutations in BCOR and CREBBP, along with a DNA methylation profile matching the “CNS tumor with EP300:BCOR(L1) fusion” methylation class." (PMID 38216991, 2024). "APC (p = 1.7e-20), BCL9 (p = 0.0006), CREBBP (p = 8.5e−5), FLCN (p = 1.39e−7), NSD2 (p = 0.002), and EP300 (p = 1.42e−6) all had significantly higher mutation rates in MSLN low expressing tumor samples compared to MSLN high expressing tumor samples." (PMID 39174744, 2024). "In this study, we investigated the dependence of EP300/CREBBP in MLL-r AML and evaluated the anti-tumor efficacy of EP300/CREBBP inhibitor." (PMID 38693103, 2024). "The test results showed that the tumor-specific mutations in this sample were as follows: BCL6, TNFAIP3, PRDM1, CREBBP, DTX1, and FOXO1." (PMID 37884941, 2023). "Recently, CREBBP LOF has also been proposed to increase the expression of CSF1 and CCL2 in DLBCL tumor cells, thereby promoting tumor-associated macrophage recruitment and polarization towards immunosuppressive macrophages." (PMID 38022603, 2023). "The specific roles of CREBBP in cancer development have only partly been defined, including pro-oncogenic as well as tumor-suppressive functions." (PMID 37407554, 2023). "CREBBP and MYCN stainings of OBs of P21 mice confirmed strong accumulation of MYCN and loss of CREBBP in tumor tissue compared to the control." (PMID 37407554, 2023). "CREBBP/EP300 participate in tumor immune regulation by modulating the function of immune cells through various pathways." (PMID 36831561, 2023). "This is consistent with reports showing that CREBBP can act as a tumor-suppressor or an oncogene in a cell type specific manner." (PMID 36991492, 2023). "CREBBP/EP300 also function as tumor suppressors, but the number of agonists and relevant preclinical studies is relatively rare, which requires further research." (PMID 36831561, 2023). "CREBBP/EP300 also participate in tumor immune responses by regulating the differentiation and function of multiple immune cells." (PMID 36831561, 2023).
tumor (continued). "Next-generation sequencing revealed six tumor-specific mutated genes (IGH/BCL6, TNFAIP3, PRDM1, CREBBP, DTX1, and FOXO1)." (PMID 37884941, 2023). "In DLBCL, CREBBP/EP300 mutations promote tumor-associated macrophage M2 polarization, thereby facilitating tumor progression in vivo and in vitro." (PMID 36831561, 2023). "Taken together, these results suggest that CREBBP/EP300 are involved in tumor immune responses by regulating immune cell functions, including Tregs differentiation, macrophage M2 polarization, and immune surveillance and killing functions of NK cells." (PMID 36831561, 2023). "From the most mutated genes, CREBBP and JMJD1C especially were more commonly mutated in the breast NET cohort compared with the IDC cohort." (PMID 36085291, 2022). "In vivo experiments validated that BMSC-EV-derived NORAD facilitated tumor growth by upregulating CREBBP via miR-877-3p." (PMID 35281474, 2022). "On the other hand, expressions of NORAD and CREBBP were augmented while miR-877-3p was diminished in tumor tissues of nude mice administered with EVs, which was abrogated by administration of EVs by silencing NORAD." (PMID 35281474, 2022). "Here, we will focus on the mutations of the histone acetyltransferase CREBBP and the methyltransferases KMT2D and EZH2 that play a key role in the FL microenvironment, and have detrimental consequences on the anti-tumor immune response." (PMID 35022084, 2022). "CREBBP is a histone acetyltransferase that plays an important role in hematopoiesis and is considered a tumor suppressor." (PMID 36422902, 2022). "Altogether, BMSC-EVs promoted tumor growth by carrying NORAD to regulate the miR-877-3p/CREBBP axis." (PMID 35281474, 2022). "Further, some studies claimed that macrophage polarization in DLBCL was associated with CREBBP/EP300 mutations and in turn promotes tumor progression." (PMID 36072582, 2022). "APOA1 and APOA2 were observed to be associated with E1A binding protein p300 (EP300) and CREB binding protein (CREBBP) which play an important role in tumor metastasis." (PMID 36428687, 2022). "In B-lymphoma murine models, xenografted tumors bearing CREBBP/EP300 mutation presented lower H3K27 acetylation, higher M2 macrophage recruitment, and more rapid tumor growth than those with CREBBP/EP300 wild-type control via FBXW7-NOTCH-CCL2/CSF1 axis." (PMID 33431788, 2021). "This was supported by the observation that the CREBBP-targeted genes were significantly upregulated in HBsAg+ tumours compared to HBsAg− tumours." (PMID 33911074, 2021). "Knockdown of CREBBP by shCBP-1 completely suppressed tumor formation in all mice, and CREBBP knockdown by shCBP-2 significantly inhibited tumor growth." (PMID 34149923, 2021). "The results showed that CREBBP knockdown suppressed tumor proliferation and promoted chemo-sensitivity via mitigating the PERK-mediated unfolded protein response (UPR)." (PMID 34149923, 2021). "Somatic mutations in CREBBP and EP300 are reported in different benign and malignant tumors, and an association between RSTS patients and tumor development has been investigated." (PMID 33807238, 2021). "CREBBP is one of the most frequently mutated genes in DLBCL and acts as a tumor suppressor of germinal center-derived lymphomagenesis by promoting transcription, counteracting the inhibition of B-cell lymphoma 6 (BCL6)." (PMID 33593440, 2021). "EP300 and its cofactor CREBBP are reported to display oncogene or tumor suppressive functions depending on the malignancy considered." (PMID 34439123, 2021). "The result indicated that CREBBP knockdown suppressed tumor proliferation both in HEY and SKOV3 cells." (PMID 34149923, 2021). "This means that gene PIK3CA does not directly regulate gene CREBBP in the normal state, and PIK3CA can affect the tumor gene CREBBP in the tumor state." (PMID 34335688, 2021). "In DLBCL, it has been shown that CREBBP/EP300 mutations are also associated with the recruitment CD68+ and CD163+ M2 macrophages to the tumor site." (PMID 35071240, 2021).
tumor (continued). "CREB-binding protein (CREBBP) is a haploinsufficient tumor suppressor that acts as a major regulator of enhancer networks in the GC, especially in the light zone, and avoids terminal B cell differentiation." (PMID 33562694, 2021). "Panobinostat has also been found to reduce the tumor volume and tumor cell proliferation in SHH MB mouse models with CREBBP (CREB-binding protein gene) mutations." (PMID 34066495, 2021). "Similar to BCOR, the fusion event involving CREBBP (cAMP-response element binding protein-binding protein) potentially promotes gliomagenesis via disruption of its tumor suppressor function." (PMID 32493417, 2020). "Inactivating mutations in CREBBP are frequently found in SCLC tissues, where it is suggested to act as a tumor suppressor." (PMID 32645997, 2020). "Of these, the most frequently mutated genes were CREBBP and CASC5 in all three tumor types, HNF1A and APC in both PDACs and PNETs, while two, four, and eight genes were mutated only in PDACs, PNETS, and INETs, respectively." (PMID 32586046, 2020). "The mutations observed in CREBBP and EP300 were largely mutually exclusive, suggesting a shared tumor suppressor function between these functional paralogs." (PMID 31827074, 2019). "STAT3, Notch1/2, Cullin1, TGF-B2, and CREBBP mediate tumor cell proliferation and therapeutic resistance, and inhibition of the Notch and TGF families sensitizes cancer cells to radiation therapy." (PMID 30546829, 2018). "These more frequently mutated instances encompassed in total 53 genes and included the experimentally characterized hotspots within the PTEN, FBXW7, SMAD4, EP300, and CREBBP tumor suppressors." (PMID 29572294, 2018). "We found that the PPARA and CREBBP expression value in HCC tissues was clearly down-regulated than in matched non-tumour tissues (P < 0.01)." (PMID 29780284, 2018). "For patient 10, the CNA profile observed in the tumour (including focal loss of CDKN2A and CREBBP) was observed in all peripheral sample types taken prior to starting chemotherapy, albeit at lower levels in plasma." (PMID 28717136, 2017). "Whole-genome sequencing of 4 and whole-exome sequencing of 71 tumor samples showed that only BCOR and CREBBP were mutated in 10% and 4% of the cases, respectively." (PMID 28099942, 2017). "Genes and related networks implicated by both data sets involved both known and novel disease mechanisms and highlighted the different roles of BRCA1 and CREBBP in the two tumor types." (PMID 27788148, 2016). "CREBBP and CD81 alterations were associated with a 2.029-fold (p = 0.048) and 0.727-fold (p = 0.018) increased risk for tumor recurrence, respectively." (PMID 25915404, 2015). "CREBBP mutant B cells stimulated less proliferation of T cells in vitro compared with wild-type B cells from the same tumour." (PMID 26146524, 2015). "CREBBP is also involved in multiple signaling pathways and in other cellular functions such as DNA repair, cell growth, differentiation, apoptosis, and tumor suppression." (PMID 25768348, 2015). "There were also two processes associated to bone “myelopoiesis of bone marrow” (associated genes NPM1, RARA) and “quantity of trabecular bone” (associated genes CREBBP, SMO)—these findings were present only in the tumour tissue." (PMID 25496518, 2014). "Though the targets of CREBBP/p300 are diverse, it seems likely that disruption of acetyltransferase ability can be a main contributor to tumor formation." (PMID 24622842, 2014). "CREBBP mutations further disrupt the downstream components of the NOTCH pathway, leading to expression of CCL2 and CSF1, which in turn promote the polarization of tumor-associated macrophages toward the immunosuppressive M2 phenotype." (PMID 40943058, 2025). "Loss of chromosome 22 was detected in two small meningothelial nests, whereas the somatic mutations in NF2 and CREBBP found in the mass-forming tumor were not present." (PMID 39066986, 2024).